CEMIP (cell migration inducing hyaluronidase 1)
Diseases named in the same sentence as CEMIP in open-access papers (continued):
Sharing a sentence is not in itself a finding about the gene and the disease.
osteosarcoma (6 papers, 2017 to 2025). A usually aggressive malignant bone-forming mesenchymal neoplasm, predominantly affecting adolescents and young adults. "Notch signalling in osteosarcoma can be indirectly activated by cell migration-inducing protein (CEMIP) that is overexpressed in osteosarcoma patients and associated with poor prognosis." (PMID 40983796, 2025). "This study investigates the effects of COS on CEMIP expression in osteosarcoma and explores the underlying mechanism." (PMID 37668818, 2023). "In this study, we found that CEMIP expression was up-regulated in tumor samples obtained from osteosarcoma patients, and its expression was associated with a poor prognosis in these individuals." (PMID 35957875, 2022). "As a result of these data, it suggests that CEMIP expression is increased and associated with the prognosis in osteosarcoma patients." (PMID 35957875, 2022). "Therefore, the aim of the present study is to investigate the effects and underlying mechanisms of COS on CEMIP expression in osteosarcoma." (PMID 37668818, 2023). "The findings of our study collectively indicate that COS, a naturally active compound, may be effective in inhibiting the expression of CEMIP, one of the main factors associated with osteosarcoma malignancy." (PMID 37668818, 2023). "This study provides evidence that COS could inhibit the expression of CEMIP in osteosarcoma, which is closely associated with tumor malignancy." (PMID 37668818, 2023). "Moreover, increased expression of CEMIP has been found to promote the progression and metastasis of osteosarcoma and has been associated with poor prognosis of osteosarcoma." (PMID 37668818, 2023). "In addition, clinical data and pathology sections from eighty osteosarcoma patients were collected for IHC measurements of CEMIP expression, the results showed that increased CEMIP expression was associated with advanced osteosarcoma stage." (PMID 35957875, 2022). "Our results provided substantial evidence that CEMIP is an oncogenic and metastatic risk for osteosarcoma, suggesting that targeting CEMIP may provide a novel strategy for osteosarcoma treatment." (PMID 35957875, 2022). "CEMIP has been linked to the pathogenesis of a variety of malignancies in previous studies; however, its role and mechanism in osteosarcoma remain unknown." (PMID 35957875, 2022). "Inhibition of CEMIP function reduces Notch signalling activation and suppresses osteosarcoma growth and metastasis in vitro and in vivo." (PMID 40983796, 2025). "Based on this, we continued to investigate the effect of COS on CEMIP expression and found that COS significantly inhibited the expression of CEMIP in osteosarcoma at both the mRNA and protein levels." (PMID 37668818, 2023). "Cell migration-inducing protein (CEMIP) plays a crucial role in the progression and malignancy of various tumor diseases, including osteosarcoma." (PMID 37668818, 2023). "Our results demonstrate that COS possesses inhibitory effects against human osteosarcoma cells and significantly suppresses CEMIP expression in vitro." (PMID 37668818, 2023). "In order to further determine the role of CEMIP in pathogenesis of osteosarcoma cells in vivo, HOS cells from shCEMIP group and control group were injected subcutaneously into nude mice respectively." (PMID 35957875, 2022). "As showing in the results, we found that silencing CEMIP significantly decreased the protein expression of Notch receptor Notch1, Notch ligand Jagged1, and Notch target gene Hes1 in osteosarcoma cells." (PMID 35957875, 2022). "To further confirm the regulatory role of Notch signaling pathway in CEMIP-regulated osteosarcoma cells growth and metastasis, we stimulated shCEMIP osteosarcoma cells using Valproic acid, a Notch signaling activator (VPA), which was dissolved in DMSO." (PMID 35957875, 2022).
osteosarcoma (continued). "In conclusion, our study demonstrated that CEMIP plays a substantial role in the progression of osteosarcoma via Notch signaling pathway, providing a promising therapeutic target in osteosarcoma." (PMID 35957875, 2022). "Mechanically, silencing CEMIP dramatically reduced osteosarcoma cells proliferation, invasion and migration in vitro, inhibited osteosarcoma cells growth and metastasis in vivo, and increased the proportion of apoptotic cells." (PMID 35957875, 2022). "First, we did not further study the downstream target genes that were directly regulated by CEMIP in osteosarcoma." (PMID 35957875, 2022). "Silencing CEMIP decreased osteosarcoma cells proliferation, migration, and invasion, but enhanced apoptosis in vitro, and suppressed tumor growth and metastasis in vivo." (PMID 35957875, 2022). "In summary, our study indicated that CEMIP was over-expressed in osteosarcoma, and correlated with the prognosis of osteosarcoma patients." (PMID 35957875, 2022). "In this study, we revealed that Notch signaling pathway is involved in CEMIP-regulated osteosarcoma, and CEMIP promotes osteosarcoma cells growth and metastasis in vitro and in vivo through activating Notch signaling pathway." (PMID 35957875, 2022). "According to our findings, CEMIP can promote osteosarcoma cells proliferation and metastasis via Notch signaling pathway." (PMID 35957875, 2022). "Although the function of CEMIP in osteosarcoma was intensively investigated, there are still some shortcomings in this study." (PMID 35957875, 2022). "In the current study, we found that CEMIP was overexpressed in osteosarcoma tissues, which was positively correlated with advanced tumor stage and poor prognosis of the disease." (PMID 35957875, 2022). "This study demonstrates that COS could inhibit the expression of CEMIP, which is closely related to osteosarcoma malignancy." (PMID 37668818, 2023). "Based on the observed inhibitory effect of COS on osteosarcoma cells, we investigated whether COS could affect the expression of CEMIP in osteosarcoma cells." (PMID 37668818, 2023). "Taken together, our findings revealed that CEMIP could promote osteosarcoma progression and metastasis through activating Notch signaling pathway in vitro and in vivo." (PMID 35957875, 2022). "Additionally, we demonstrated that Notch signaling pathway was involved in the CEMIP-regulated pathogenesis of osteosarcoma." (PMID 35957875, 2022). "Thus, our findings indicated that silencing CEMIP would be able to suppress osteosarcoma growth and metastasis in vivo." (PMID 35957875, 2022). "As a result of these findings, we concluded that CEMIP could promote the invasion and migration of osteosarcoma cells in vitro." (PMID 35957875, 2022). "Following that, the effect of CEMIP on osteosarcoma was investigated, and it was discovered that suppressing CEMIP could inhibit osteosarcoma growth and metastasis in vitro and in vivo." (PMID 35957875, 2022). "CEMIP promoted osteosarcoma cells progression and metastasis through activating Notch signaling pathway, thus suggesting that CEMIP could be a potential target for gene therapy of osteosarcoma." (PMID 35957875, 2022). "Similarly, osteosarcoma patients with overexpressed CEMIP have a very poor prognosis." (PMID 37668818, 2023). "The result showed that the expression of CEMIP in osteosarcoma tissues was significantly higher than that in normal tissues, and the prognosis of patients with high CEMIP expression was worse than that of patients with low CEMIP expression, which were consistent with our findings." (PMID 35957875, 2022). "Finally, the possible mechanism of CEMIP promoting the osteosarcoma pathogenesis was explored, and it was demonstrated that silencing CEMIP may inhibit the carcinogenesis of osteosarcoma via attenuating Notch signaling pathway." (PMID 35957875, 2022). "However, the role and mechanism of CEMIP in osteosarcoma remain unclear." (PMID 35957875, 2022).
osteosarcoma (continued). "However, the significant of CEMIP and its possible mechanism in osteosarcoma remain unknown." (PMID 35957875, 2022). "Therefore, based on the preliminary evidence of COS’s anti-tumor activity in osteosarcoma, we investigated the effect of COS on CEMIP expression." (PMID 37668818, 2023). "Recently, high expressions of CEMIP and hyaluronan were reported to be as poor prognostic factors for osteosarcoma, but in which no verification or exact mechanism were clarified." (PMID 35957875, 2022). "This study investigated the role of CEMIP in the progression and metastasis of osteosarcoma, CEMIP was found to be overexpressed in osteosarcoma tissues when compared to adjacent non-tumor tissues, and its expression was positively associated with a poor prognosis in osteosarcoma patients." (PMID 35957875, 2022). "Given high expression of CEMIP in HOS and U2OS, we established CEMIP silencing osteosarcoma cells (shCEMIP group) using three kinds of shRNA and its negative control cells (Control group), and the mock group is parental osteosarcoma cells without lentivirus (Mock group)." (PMID 35957875, 2022).
pancreatic ductal adenocarcinoma (6 papers, 2017 to 2023). An infiltrating adenocarcinoma that arises from the epithelial cells of the pancreas. "Overexpression of either TMEM2 or CEMIP is a poor prognosis indicator in pancreatic ductal adenocarcinoma and siRNA knockdown of CEMIP expression leads to a decrease in cell migratory capacity." (PMID 33809973, 2021). "Indeed, the increase of CEMIP expression is observed after stimulation with TNF-α in OA chondrocytes, IL-6 in Crohn’s disease fibroblasts and IL-1β in pancreatic ductal adenocarcinoma cell line." (PMID 35474501, 2022).
breast tumor (5 papers, 2012 to 2023). "Recently, the expression of CEMIP has been more specifically targeted using the hydrogel-based delivery of CEMIP-specific short hairpin RNAs, which elicited anti-tumor and –metastasis effects in a spontaneous breast tumor model." (PMID 36291875, 2022). "Similar observations supporting a functional role for CEMIP in metastasis have been made using hepatocellular, gastric, and breast tumor models in vivo." (PMID 36291875, 2022).
chondrosarcoma (5 papers, 2022 to 2025). A malignant cartilaginous matrix-producing mesenchymal neoplasm arising from the bone and soft tissue. "CEMIP also mediated IL-1β expression through Erk pathway activation and NF-KB translocation in chondrosarcoma cell line." (PMID 35474501, 2022). "Koike found the forced expression of CEMIP effectively suppressed the tumorigenicity of low‐grade chondrosarcoma with abundant hyaluronan." (PMID 35957875, 2022). "In addition to these Hyal1 and/or testicular hyaluronidase inhibitors, the panel also included ipriflavone, an isoflavone that has been suggested to influence HA metabolism in CEMIP-expressing chondrosarcoma cells." (PMID 39851529, 2025).
idiopathic pulmonary fibrosis (5 papers, 2021 to 2025). Idiopathic pulmonary fibrosis (IPF) is a nonneoplastic pulmonary disease that is characterized by the formation of scar tissue within the lungs in the absence of any known cause. "Recent findings have demonstrated that CEMIP exhibits pro-fibrotic functions and acts as a therapeutic target of pirfenidone for the treatment of mild-to-moderate idiopathic pulmonary fibrosis (IPF)." (PMID 36639658, 2023). "Pirfenidone is an anti-fibrotic and anti-inflammatory agent used to treat idiopathic pulmonary fibrosis, which suppresses CEMIP levels and increases HA levels in the lungs of patients." (PMID 36291875, 2022). "Recently, high plasma level of CEMIP was found in patients suffering from idiopathic pulmonary fibrosis (IPF) compared to controls." (PMID 35474501, 2022). "In idiopathic pulmonary fibrosis, CEMIP silencing reduced the production of collagen, thereby reducing the ability of lung fibroblasts to proliferate and migrate." (PMID 34338150, 2021). "Notably, a recent study has demonstrated a potent effect of CEMIP on the aggravation of lung fibrosis by stimulating ECM production and stiffness." (PMID 36639658, 2023).
papillary thyroid cancer (5 papers, 2020 to 2023). "The role of CEMIP in papillary thyroid carcinoma (PTC) remains unknown." (PMID 35543351, 2022).
atherosclerosis (4 papers, 2019 to 2022). A disease characterized by the build-up of fatty material and calcium deposition in the arterial wall resulting in partial or complete occlusion of the arterial lumen. "In atherosclerosis, CEMIP was reported to regulate the proliferation and migration of vascular smooth muscle cells." (PMID 34804124, 2021).
colorectal adenoma (4 papers, 2012 to 2022). An adenoma that arises from the colon or rectum. "Moreover, CEMIP RNA levels have been shown to be significantly higher in the blood from patients with colorectal adenomas or more advanced CRC than in healthy controls, indicating that CEMIP could serve as a plasma RNA biomarker in this context." (PMID 36291875, 2022).
metastatic disease (4 papers, 2021 to 2024). "Interestingly, data obtained from quantification of CEMIP in patient samples showed that metastatic tumors with high levels of CEMIP are linked to poor survival when compared to those with low levels of CEMIP." (PMID 34639239, 2021). "Nonetheless, our findings, in conjunction with previous studies, suggest that cell-type specific CEMIP inhibitors have the potential to treat metastatic disease." (PMID 39454959, 2024). "β-catenin and CEMIP are Wnt-related proteins, and a recent study reported that CEMIP is present in high levels in metastatic tumor-derived exosomes and promotes tumor metastasis by creating a metastatic environment." (PMID 34728784, 2021). "Numerous studies have reported high expression levels of CEMIP in cancer cells and the relationship of CEMIP with invasive and metastatic disease mediated through the Wnt/β-catenin signaling pathway." (PMID 34728784, 2021). "Only a few studies have investigated the utility of inhibiting CEMIP to combat cancer and metastatic disease, and given the functional role that CEMIP plays in the process of tumorigenesis and metastasis, this could be a promising therapeutic avenue to explore in the future." (PMID 36291875, 2022).
Crohn disease (3 papers, 2020 to 2022). A gastrointestinal disorder characterized by chronic inflammation involving all layers of the intestinal wall, noncaseating granulomas affecting the intestinal wall and regional lymph nodes, and transmural fibrosis. "Moreover, CEMIP induces fibrosis of Crohn disease fibroblasts through the depolymerization of HA into small HA fragments with pro-inflammatory and pro-fibrotic properties." (PMID 35474501, 2022). "In OA synoviocytes and in Crohn’s disease fibroblasts, IL-6 significantly up-regulated CEMIP level." (PMID 35474501, 2022).
deafness (3 papers, 2022 to 2024). An inherited or acquired condition characterized by the complete loss of the ability to hear from one or both ears. "Interestingly, experiments suggest that TMEM2 activity is calcium dependent and TMEM2 has been previously studied for its structural similarities with the CEMIP deafness gene candidate." (PMID 38459354, 2024).
gastric adenocarcinoma (2 papers, 2012 to 2021). "CEMIP expression was negatively correlated with B cell and CD4 + T cell infiltration in patients with stomach adenocarcinoma (STAD) (r = −0.2042, p = 7.72e-05 and r = −0.13, p = 1.31e-0, respectively)." (PMID 34338150, 2021).
glioblastoma (2 papers, 2020 to 2022). The most malignant astrocytic tumor (WHO grade IV). "Interestingly, in this model, the loss of CEMIP expression in stromal cells reduces macrophage infiltration into the glioblastoma tissue, which is linked to an accumulation of HA." (PMID 36291875, 2022). "Conversely, the loss of CEMIP increases the levels of HMW-HA, both in glioblastoma cells in vitro and in the respective tumors in vivo, which is linked to reduced tumor growth." (PMID 36291875, 2022). "In glioblastomas, CEMIP has been shown to contribute to macrophage migration, M2 polarization, and the release of pro-tumorigenic factors that promote tumor growth." (PMID 36291875, 2022). "CEMIP may be related to brain function and development, MEK/ERK-induced Schwann-cell dedifferentiation, immune response in glioblastoma, and WNT signaling." (PMID 32508873, 2020).
glioma (2 papers, 2023). A benign or malignant brain and spinal cord tumor that arises from glial cells (astrocytes, oligodendrocytes, ependymal cells). "The transplantation of human glioma cells knocked out of CEMIP into mice with CEMIP deficiency limited the proliferation and migration of tumor cells, and the penetration of macrophages in the glioma tissues of mice with CEMIP deficiency was decreased." (PMID 37662915, 2023).
intervertebral disc degeneration (2 papers, 2022 to 2025). "Downregulation of miR-486-3p mediates CEMIP promoting NPC proliferation and extracellular matrix production in intervertebral disc degeneration." (PMID 35484551, 2022).
Myocardial fibrosis (2 papers, 2023 to 2025). "Moreover, knockdown of BMP6 aggravates myocardial fibrosis after MI mainly through upregulating the expression of AP‐1/CEMIP." (PMID 37313693, 2023). "Consequently, it is reasonable to suspect that BMP6 inhibited CEMIP expression by suppressing AP‐1 transcriptional activity, thereby slowing the progression of myocardial fibrosis after MI." (PMID 37313693, 2023). "Therefore, we speculate that CEMIP may represent a potential mechanism through which silencing BMP6 expression can aggravate myocardial fibrosis." (PMID 37313693, 2023).
Obesity (2 papers, 2025). Accumulation of substantial excess body fat. "Obesity has also been linked to altered HA catabolism (e.g., hyaluronidase [HYAL]1/2, cell migration-inducing hyaluronidase 1/transmembrane protein 2 [CEMIP/TMEM2]) and higher systemic HA turnover, which may influence mammary HA levels." (PMID 41305610, 2025).
schwannoma (2 papers, 2023 to 2024). A benign, usually encapsulated slow growing tumor composed of Schwann cells. "CEMIP, THSD4, and GPC6 were among the topmost DE genes in the Schwannoma nuclei." (PMID 36865335, 2023).
skin infection (2 papers, 2020 to 2023). An inflammatory process affecting the skin, caused by bacteria, viruses, parasites, or fungi. "They found that CEMIP loss increases inflammation and antimicrobial activity following a skin infection and that CEMIP−/− mice challenged with S. aureus had higher IL-6 and neutrophil infiltration." (PMID 36902251, 2023).
small cell lung carcinoma (2 papers, 2022 to 2023). Small cell lung cancer (SCLC) is a highly aggressive malignant neoplasm, accounting for 10-15% of lung cancer cases, characterized byrapid growth, and early metastasis. "CEMIP functioned as a metastatic promoter in small cell lung cancer." (PMID 35543351, 2022).
Alzheimer disease (1 paper, 2017). A progressive, neurodegenerative disease characterized by loss of function and death of nerve cells in several areas of the brain leading to loss of cognitive function such as memory and language. "This cell-based litmus gene assay identified six genes (CCL20, CEMIP, IL1B, IL8, PRG2, PTGS2) as potential biomarkers of plasma quality control and the SPC25 gene as a diagnostic biomarker of Alzheimer’s disease (AD)." (PMID 29203810, 2017).
brain cancer (1 paper, 2022). A primary or metastatic malignant neoplasm affecting the brain. "Cell migration inducing hyaluronidase 1 (CEMIP) catalyzes catabolism of hyaluronan, and participates in regulation of hyaluronic acid-rich organ diseases, including ovary, testis, lung, skin, and brain cancers." (PMID 35543351, 2022).
cervical tumors (1 paper, 2022). "Additionally, it was reported that CEMIP could induce tumor angiogenesis via interacting with the EGFR pathway of cervical tumors in a NF-κB dependent manner." (PMID 35957875, 2022).